NME1 (NME/NM23 nucleoside diphosphate kinase 1)
Diseases named in the same sentence as NME1 in open-access papers (continued):
Sharing a sentence is not in itself a finding about the gene and the disease.
triple-negative breast carcinoma (3 papers, 2014 to 2021). An invasive breast carcinoma which is negative for expression of estrogen receptor (ER), progesterone receptor (PR), and human epidermal growth factor receptor 2 (HER2). "MDA-MB-231T triple-negative breast cancer cells were transfected with Flag-tagged human NME1, NME2, murine Nme1 or an empty vector (V), and pools of Flag-positive cells were collected." (PMID 29535799, 2018). "When tumors were stratified into luminal A/B, HER2 + and triple-negative breast cancer (TNBC) subtypes, cytoplasmic and membranous NME1 levels remained significantly lower in the invasive component as compared to the adjacent DCIS foci, irrespective of the molecular subtype." (PMID 34012098, 2021).
Alzheimer disease (2 papers, 2020 to 2021). A progressive, neurodegenerative disease characterized by loss of function and death of nerve cells in several areas of the brain leading to loss of cognitive function such as memory and language. "NME1 expression has also reported to be downregulated in Alzheimer disease (Cieślak and Wojtczak, 2018)." (PMID 32853992, 2020).
breast adenocarcinoma (2 papers, 2014 to 2019). "It has been demonstrated that the human Nme1 suppresses anchorage independent growth in soft agar in human breast adenocarcinoma cell lines MDA-MB-435 and MDA-MB-231." (PMID 31877804, 2019).
Carcinoma in situ (2 papers, 2008 to 2022). "Here we studied one of its derivatives, the in situ carcinoma cells, MCF10DCIS.com, in which NME1 or NME2 were ablated." (PMID 36111347, 2022).
colitis (2 papers, 2023 to 2024). Inflammation of the colon. "Moreover, mice carrying Nme1‐depleted macrophages showed more severe colitis and greater impairment of the epithelial layers." (PMID 36922750, 2023). "To explore whether macrophages overexpressing Rhoh or Nme1 could protect mice from developing colitis, we infected BMDMs with Rhoh‐ or Nme1‐lentivirus." (PMID 36922750, 2023).
esophageal cancer (2 papers, 2014 to 2016). A primary or metastatic malignant neoplasm involving the esophagus. "Most studies reported that over-expression of NME1 was associated with a better overall survival of various cancers, like liver, colorectal, breast, lung, and esophageal cancers." (PMID 27518571, 2016).
gallbladder carcinoma (2 papers, 2016 to 2020). "In gallbladder carcinoma, MSI was an early stage molecule marker and LOH was a molecule marker for the deteriorism which could inhibit the expression of NME1 in local tissues." (PMID 27518571, 2016).
glioblastoma (2 papers, 2022 to 2023). The most malignant astrocytic tumor (WHO grade IV). "Among the enzymes associated with nucleotide synthesis, RRM1 and NME1 are significantly upregulated in glioblastoma." (PMID 36175487, 2022). "We showed that RRM1 and NME1 were significantly upregulated in both pyrimidine and purine synthesis pathways in glioblastoma, elevated more than twofold compared to near-normal brain, suggesting that these enzymes might offer therapeutic targets for the treatment of glioblastoma." (PMID 36175487, 2022).
glioma (2 papers, 2024 to 2025). A benign or malignant brain and spinal cord tumor that arises from glial cells (astrocytes, oligodendrocytes, ependymal cells). "First, NME1 is a negative regulator of migration in different cancers such as oral squamous cell carcinoma, liver, glioma, breast, and colon cancer." (PMID 39063217, 2024). "NME1 is poorly expressed in glioma tissue at the protein and RNA levels." (PMID 39063217, 2024). "Overexpression of NME1 negatively regulates the protein kinase C (PKC) signaling pathway and inhibits cell proliferation in glioma." (PMID 39063217, 2024).
metastatic melanoma (2 papers, 1996 to 2020). A melanoma that has spread from its primary site to another anatomic site. "NME1 was first described as a metastasis suppressor in a study comparing RNA levels in mouse metastatic melanoma cell lines with non-metastatic cells, which showed that Nm23/NME1 expression was downregulated in the metastatic cells." (PMID 32823988, 2020).
Sepsis (2 papers, 2022 to 2025). Sepsis is defined as life-threatening organ dysfunction caused by a dysregulated host response to infection. "As lipid metabolism is impaired in sepsis, NME1 may be involved in the pathophysiology of sepsis, in accordance with our finding showing that NME1 expression is elevated in sepsis patients compared with healthy controls." (PMID 35265105, 2022). "Meanwhile, the present study identified eight metabolism-related genes (NME1, NME6, POLD4, POLE4, POLR2J, POLR2L, ADCY3, and ENTPD1) in patients with sepsis and the identified metabolism-related genes may represent diagnostic and therapeutic biomarkers of sepsis." (PMID 35265105, 2022).
squamous cell carcinoma (2 papers, 2008 to 2020). A carcinoma arising from squamous epithelial cells. "However, reduced NME1 expression was found to have a significantly higher prevalence in squamous cell carcinoma (46%) than in adenocarcinoma (34%), and the difference was statistically significant (p = 0.01)." (PMID 32977620, 2020). "Reduced NME1 expression had a negative effect on RFS in adenocarcinoma (p < 0.0001) and in squamous cell carcinoma (p < 0.0001)." (PMID 32977620, 2020).
acute renal failure (1 paper, 2015). "Thus, the AR-signature expediently included major markers of acute renal failure (STMN1) as well as demonstrated alterations (NME1, Ras-Raf), which have been previously associated with the kidney transplantation specific treatments." (PMID 26962294, 2015).
anemia (1 paper, 2020). A reduction in the number of red blood cells, the amount of hemoglobin, and/or the volume of packed red blood cells. "NME2 promotes the development of erythropoiesis, because the iron transport receptor TfR1 in the red blood cells of Nme1/Nme2-deficient mice is down-regulated, characterized by hypoplasia, severe anemia, and perinatal death." (PMID 33281799, 2020).
asthma (1 paper, 2024). "Chelidonium majus relieved OVA-induced asthma in rats by regulating the Alox15, P4ha1, Pla2g16, Pde3a, Nme1, Entpd8 and Adcy9 genes expression to restore the disorders in energy metabolism and inflammation." (PMID 38671520, 2024).
bone metastasis (1 paper, 2020). Transfer of a neoplasm from its primary site to bones. "In contrast, reduced NME1 expression has been found to be associated with bone metastasis and poor survival in patients with pulmonary adenocarcinoma." (PMID 32977620, 2020).
dengue (1 paper, 2019). "Both NME1 and IFIT3 were expressed by CD4+ T cells from dengue-infected patients." (PMID 31624246, 2019).
Fanconi anemia (1 paper, 2023). Fanconi anemia (FA) is a hereditary DNA repair disorder characterized by progressive pancytopenia with bone marrow failure, variable congenital malformations and predisposition to develop hematological or solid tumors. "These genes include DDIT3 (DNA damage-inducible transcript 3), FANCM (Fanconi anemia, complementation group M), Merlin tumor suppressor, NME1 (NME/NM23 nucleoside diphosphate kinase 1), SMAD4." (PMID 37239070, 2023).
Intraventricular hemorrhage (1 paper, 2022). Bleeding into the ventricles of the brain. "Mothers of FGR neonates who developed neurological complications and intraventricular hemorrhage (IVH) had statistically higher NME1 concentrations during pregnancy and significantly lower placental CLN4 expression than mothers of FGR neonates without neurological abnormalities." (PMID 36430274, 2022).
meningioma (1 paper, 2017). A generally slow growing tumor attached to the dura mater. "NME1, NFE2, SFN, PTN, CALN1, GABRA5 and several components involved in neural differentiation and receptors associated with neural transmitter were also found to illicit an autoimmune response in the meningioma patients indicating that there could be some alterations in these components." (PMID 28938569, 2017).
mesothelioma (1 paper, 2009). A usually malignant and aggressive neoplasm of the mesothelium which is often associated with exposure to asbestos. "The local invasive, non-metastatic phenotype of mesothelioma, could partly be due to overexpression of the known metastasis suppressors NME1 and NME2." (PMID 19662092, 2009).
Myalgia (1 paper, 2025). "Specifically, when NME1 levels decreased from 15 min to 24 h postexercise (Log2FC < 0), myalgia became worse (Δ > 0), suggesting that NME1‐loaded EVs are involved in signalling pathways that regulate cellular and muscle recovery after stress or injury, including exercise." (PMID 40465195, 2025). "We also found that the 24 h/15 min ratio for NME1, a protein involved in nucleoside triphosphate synthesis and cellular stress responses, had a strong and significant negative correlation with the change in myalgia after exercise in ME/CFS patients." (PMID 40465195, 2025).
Peri-Implantitis (1 paper, 2019). An inflammatory process with loss of supporting bone in the tissues surrounding functioning DENTAL IMPLANTS. "Three leader genes (PSMD10, SOS1, WASF3), eight cross-talk genes (PSMD10, PSMD6, EIF2S1, GSTP1, DNAJC3, SEC61A1, MAPT, and NME1), and one signaling pathway (IL-17 signaling) emerged as peri-implantitis and T2DM linkage mechanisms." (PMID 31275749, 2019).
pituitary adenoma (1 paper, 2018). "In pituitary adenomas, NME1 expression inversely correlates with tumor extension into the cavernous sinus, but there are no data available on its expression pattern in different pituitary adenoma subtypes." (PMID 29507682, 2018).
somatotropinomas (1 paper, 2018). "In addition, upregulation of NME1 (2.16-fold change, P = 0.03) and HSPA9 (2.37-fold change, P = 0.05) was observed in AIPmut positive somatotropinomas, compared with normal pituitary." (PMID 29507682, 2018).
viral infection (1 paper, 2018). "Low expression of NME1 also results in decreased antiviral activity in host cells, which indicates why patients with tumors are more susceptible to viral infection." (PMID 30158514, 2018).
tumor (220 papers, 1992 to 2026). "One study showed that NME1 RNA and protein expression are associated with increased tumor size and local invasion in colorectal cancer." (PMID 39063217, 2024). "Nevertheless, this ‘partial’ EMT phenotype is more metastatic than the fully mesenchymal state, providing an explanation for the high metastatic potential of NME1-deficient tumor cells." (PMID 37353690, 2023). "As NME1 is specifically reduced or lost at the invasive front of tumors, the role of the tumor stroma, in particular the role of cancer-associated fibroblasts in regulating NME1 levels remains to be explored." (PMID 33918324, 2021). "Whereas numerous studies support the conclusion that loss of NME1 expression correlates with metastasis and poor clinical prognosis in many types of human tumor, the role of its highly homologous isoform, NME2, in malignancy is only poorly documented." (PMID 33918324, 2021). "Numerous studies have shown that loss of NME1 expression correlates with metastasis and poor clinical prognosis in several types of human tumor, mainly those of epithelial origin." (PMID 33918324, 2021). "NME1 expression is associated with regulation of genes correlated with adult cancer metastases, and NME1 depletion enhances tumor metastases in xenograft models, suggesting a role for NME1 as a suppressor of metastasis." (PMID 32392889, 2020). "Some tumor-associated stromal cells can produce tumor suppressor factors, such as nucleoside NME1, Kangai 1 (KAI1/CD82) and IL-25, in the tumor microenvironment, and these activities can restrict the development or metastasis of surrounding tumor cells." (PMID 28674499, 2017). "Only in GC and CRC, increased NME1 expression was significantly associated with well tumor differentiation (OR = 0.34, 95%CI:0.23–0.50, P<0.00001, I2 = 0%, Ph = 0.48 and OR = 0.67, 95%CI:0.47–0.93, P = 0.02, I2 = 65%, Ph = 0.003, respectively." (PMID 27518571, 2016). "In addition, immunohistochemistry staining confirmed the loss of NME1 expression in tumor xenografts generated from NME1 knockout cells (lower panel KO NME1#A)." (PMID 34012098, 2021). "The results showed that statistically significant association was found between NME1 expression and the tumor differentiation, N status and Dukes’ stage of patients with digestive system cancers, while no significance was found in overall survival, disease-free survival and TNM stage." (PMID 27518571, 2016). "Functional validation of such findings in CRC xenograft models demonstrated that NME1 inhibits migration and reduces stemness, confirming its importance in tumor biology." (PMID 41450739, 2025). "The focus of the investigation was concentrated on the biological attributes of NME1 + epi in cancer, a lens narrowed further by the exclusive study of a singular tumor type." (PMID 39075485, 2024). "Our examination revealed that the spatial nucleotide metabolism of tumor cells has been correlated with NME1." (PMID 39075485, 2024). "We previously found that NME1 is the most significantly nucleotide metabolism-related gene in tumor epithelial cells." (PMID 39075485, 2024). "In accordance with existing literature, NME1 has been recognized as a suppressor of metastasis, inhibiting tumor migration." (PMID 39075485, 2024). "The nucleoside diphosphate kinase 1 (NME1) and netrin 1 receptor (DCC) genes have been associated with resistance against tumorigenesis and tumor metastasis." (PMID 38556604, 2024). "The association of NME1 and Db1-1 causes inactivation of CDC42 and thereby inhibits migration and tumor progression." (PMID 39063217, 2024). "Some studies have suggested the role of NME1 as a protein kinase or histidine kinase in promoting tumor growth and cell proliferation." (PMID 39063217, 2024). "Overexpression of NME1 in invasive tumor cell lines that have low levels of endogenous NME1 expression reduces the migratory and invasive potential of the cells." (PMID 37353690, 2023).
tumor (continued). "These exosomes altered the endocytic pathways of receiving tumor cells via NME1, decreasing their motility and migration in vitro more than exosomes from control transfectants." (PMID 37970212, 2023). "Silencing NME1 in epithelial tumor cells results in an intermediate phenotype with both epithelial and mesenchymal features, refered to as a ‘partial’ EMT." (PMID 37353690, 2023). "Bioinformatic analyses of RNA‐seq data from PMIS‐miR‐210 SW620 cells and tumours revealed several new genes were upregulated, including the tumour suppressor NME1." (PMID 36116139, 2022). "We used the PMIS‐miR‐210 system to make stable cell lines and to inhibit tumour growth and identified the NME1 tumour suppressor regulated by an miR‐210/XIST pathway." (PMID 36116139, 2022). "NME1 can regulate gene expression by binding to promoter/enhancer regions of genes that contribute to tumour metastasis suppressor function." (PMID 36116139, 2022). "We provide evidence for the regulation of NME1, a tumour suppressor, through miR‐210/XIST‐mediated epigenetic mechanism." (PMID 36116139, 2022). "In identical experiments, we show that the tumour suppressor NME1 is also increased in the recipient cells at 1/1 and 0.5/1 ratios." (PMID 36116139, 2022). "Some size differences were also found with larger tumors obtained upon injection of NME2 KO cells, which correlated with higher percentage of PCNA-positive cells in NME2-KO tumor xenografts as compared to NT or NME1-KO tumors." (PMID 34012098, 2021). "Strikingly, at later time-point (i.e. 7 weeks after injection), immunostaining revealed that invasive tumor xenografts obtained upon injection of control MCF10DCIS.com cells expressed low NME1 levels, in contrast to in situ tumors that were frankly positive." (PMID 34012098, 2021). "Several enzymes linked to accumulated metabolites in the malignant cells were found upregulated in tumor tissue datasets, particularly NME1 and SHMT2 mRNA expression." (PMID 33917317, 2021). "Whereas the involvement of NME1 in tumor invasion and metastasis has been widely addressed, its role and the role of NME2 in EMT has hardly been studied." (PMID 33918324, 2021). "Strikingly, NME1 level was also strongly decreased in microinvasive foci (a relatively rare tumor subset corresponding to early loco-regional invasion with no invasive focus > 1 mm), relative to the in situ component from the same specimen." (PMID 34012098, 2021). "The ability of NME1 or NME2 to influence tumor invasion was evaluated using the intraductal xenograft model involving the injection of human MCF10DCIS.com cells into the primary duct of mouse mammary glands." (PMID 34012098, 2021). "NME1 was initially identified as a suppressor of tumor metastasis, and recent studies have identified critical intracellular interactions linking NME1 to tumor cell motility and metastatic spread." (PMID 32392889, 2020). "In patients with HCC and in two animal models of HCC, NME1 expression was found upregulated in comparison with non-tumor tissue, while knocking-out NME1 resulted in an increased number of lung metastasis." (PMID 32183400, 2020). "Nucleoside diphosphate kinase A (NME1/NDPK-A) is a tumor suppressor with increased expression in different PDAC datasets and in other cancers types." (PMID 32197468, 2020). "More recently, extracellular activities of NME1/2 proteins have also been reported, including a tumor- promoting function." (PMID 31427986, 2019). "AWD, or its mammalian homolog NME1, has also been identified as a conserved metastasis suppressor by regulating tumor cell motility and invasion." (PMID 31278345, 2019). "NME1 was the 1st metastasis suppressor gene identified and together with NME2 is mostly implicated in tumor progression." (PMID 31427986, 2019). "Several studies showed that NME1/2 intracellular content is correlated with either lowered or enhanced metastatic abilities depending on tissue context of the developing tumor." (PMID 31427986, 2019).